MAPK14 (mitogen-activated protein kinase 14)
Diseases named in the same sentence as MAPK14 in open-access papers (continued):
Sharing a sentence is not in itself a finding about the gene and the disease.
atherosclerosis (21 papers, 2011 to 2026). A disease characterized by the build-up of fatty material and calcium deposition in the arterial wall resulting in partial or complete occlusion of the arterial lumen. "We focused on MAPK14 (encoding p38) in this study, as it plays essential roles in inflammation and atherosclerosis." (PMID 35755441, 2022). "Previous studies reported that MAPK14 is implicated in the pathogenesis of many inflammatory-driven conditions, including atherosclerosis." (PMID 33777109, 2021). "In summary, we discovered that activated platelets could remotely modulate ET-1 and VEGFA levels in vascular endothelial cells through the release of miR-200a-3p-containing PMVs via targeting MAPK14, which provides a potential miRNA-based therapeutic strategy for atherosclerosis related diseases." (PMID 35755441, 2022). "Moreover, inhibition of a key signaling molecule of the p38α MAPK/MAPK14 might prevent inflammatory cascades in atherosclerosis." (PMID 30021655, 2018). "In a previous study, network pharmacology was utilized to examine the therapeutic roles of canagliflozin and dapagliflozin in atherosclerosis, revealing that these drugs act by targeting key molecules such as Akt1, MAPK1, MAPK14, SRC, and EGFR." (PMID 40141782, 2025).
diabetes (20 papers, 2007 to 2026). "In conclusion, we propose that MAPK14 is associated with DFUs in a Scottish cohort with diabetes using a GWAS approach." (PMID 28672053, 2017). "Chronic activation of MAPK14 signaling pathway has been implicated in the development of adaptive and maladaptive response in skeletal muscle pathologies, such as diabetes and protein catabolism, and physiological states, such as growth and differentiation." (PMID 27482297, 2016). "Studies have shown that two variations (rs3761980 and rs80028505) associated with diabetic neuropathy were located near MAPK14, and it was associated with an increased risk of diabetic foot ulcer in the GoDARTS (Genetics of Diabetes Audit and Research Tayside, Scotland) project." (PMID 39534794, 2024). "It has been shown that MAPK14 plays an important regulatory role in diseases (e.g., pneumonia, acute lung injury, diabetes mellitus) and that inhibition of this pathway is an effective measure to alleviate the level of the inflammatory response and oxidative stress in disease states." (PMID 36188533, 2022). "Moreover, it was demonstrated that MAPK14 had a proinflammatory gene that was significantly up-regulated in type 2 diabetes mellitus and CHD." (PMID 35906673, 2022). "After RT-qPCR analysis, it was found that the mRNA expression of VEGFA, KDR, MAPK14, and PPARA showed significant differences between normal and diabetes mellitus mice, with a retracement after FBT treatment." (PMID 38304230, 2023).
lung cancer (18 papers, 2006 to 2025). A malignant neoplasm involving the lung. "The target relationship between miR-424-5p and MAPK14 was predicted from public databases and has been confirmed in lung injury associated with the risk of lung cancer." (PMID 40500789, 2025). "A network pharmacology study identified MAPK14 as a therapeutic target of dauriporphine, and MAPK1 was also demonstrated to show a close association with the onset and development of lung cancer." (PMID 40500789, 2025). "The anti-lung cancer effect of dauriporphine was displayed through upregulation of miR-424-5p, which inhibits the effect of MAPK14 in cancer progression." (PMID 40500789, 2025). "This study demonstrated the inhibitory effect of dauriporphine on the viability, motility, and energy metabolism of lung cancer cells, and the miR-424-5p/MAPK14 axis was revealed as the downstream molecular mechanism." (PMID 40500789, 2025). "The findings suggested that GYP might exert anticancer effects in lung cancer and enhance the effects of chemotherapeutic agent cisplatin through the MAPK14/STAT3 signaling pathway." (PMID 36532716, 2022). "Network analysis and metabolomics combined with western blot demonstrated that GYP might exert anti-lung cancer effects as well as enhance the pharmacological effects of the chemotherapeutic agent cisplatin through the MAPK14/STAT3 signaling pathway." (PMID 36532716, 2022). "Therefore, the miR-424-5p/MAPK14 axis was hypothesized to mediate the potential anti-lung cancer effect of dauriporphine, which lacks direct evidence." (PMID 40500789, 2025). "The potential therapeutic targets of bufalin included MDM2, PIK3CA, MAPK14, and MTOR, which can induce cell death through various mechanisms and exert anticancer properties against lung cancer, liver cancer, and other tumors." (PMID 32148531, 2020). "Additionally, genes involved in the MAPK signaling pathway include BRAF, c-Jun, ERK, JNK, MAP2K1, MAP2K4, MAPK14, and KRAS, which are genes affected by MPs in lung cancer cells." (PMID 41378310, 2025). "In order to investigate how GYP exerts its anti-LC effects by regulating metabolites and metabolic pathways as well as enhancing the anti-lung cancer effects of chemotherapeutic agents, the relative contents of STAT3, EGFR, MAPK14, and TYMS between the six groups were analyzed by western blot." (PMID 36532716, 2022).
melanoma (18 papers, 2008 to 2025). A malignant, usually aggressive tumor composed of atypical, neoplastic melanocytes. "Indeed, MAPK14 is up-regulated in BRAF-inhibition-resistant melanoma in mouse models, while MAPK11 abrogation promotes radiosensitivity in A549, MCF7, and HCT-116 cells." (PMID 39666682, 2024). "On the other hand, the top downregulated genes formed 4 subgroups and were related to melanogenesis (Wnt5a, Mitf, Pomc, Mc1r, Kit), melanoma (Fgf9, Fgf12, Fgf2), MAPK signaling pathway (Ncam1, Prkcb, Map3k4, Pla2g4a, Mapk14, Mapk11), and aging (Tgfbr1, Il6, Nox4)." (PMID 36555664, 2022). "Moreover, we constructed a miRNA–miRNA interaction network using the miRNet tool, revealing key regulatory genes in melanoma, including PLAG1, TGFBR2, CDKN2A, MAPK14 and MYC, which exhibited significant degrees and betweenness centrality in the network analysis." (PMID 39823244, 2025).
colorectal cancer (17 papers, 2013 to 2025). A primary or metastatic malignant neoplasm that affects the colon or rectum. "The main factors affecting Mapk14 mRNA expression in colorectal cancer are DNA methylation and CNV alteration, while gene mutation is not a major factor." (PMID 35141222, 2022). "In conclusion, our findings revealed that Mapk14 has a predictable effect on clinical features and is associated with the immune microenvironment of colorectal cancer." (PMID 35141222, 2022). "We comprehensively investigated Mapk14 expression levels as well as DNA methylation, gene mutations and copy number changes in colorectal cancer." (PMID 35141222, 2022). "In conclusion, this study confirms that Mapk14 is an oncogene that is highly expressed in colorectal cancer clinicopathology." (PMID 35141222, 2022). "A Sankey diagram was used to show the trend of high and low expression of the Mapk14 gene for different clinical characteristics, such as stage, age and sex, in colorectal cancer patient samples and the survival of colorectal cancer patients." (PMID 35141222, 2022). "The IHC results showed that Mapk14 was expressed at higher levels in the colorectal cancer tissue of patients with clinical stages I, II, III and IV than in normal tissues." (PMID 35141222, 2022). "According to the prognostic impact of Mapk14 on colorectal cancer samples, the samples were ranked from high to low Mapk14 expression and the cancer samples were divided into high and low expression groups." (PMID 35141222, 2022). "Next, we further evaluated the relevance of Mapk14 in the clinicopathological features of colorectal cancer patients based on the clinical pathologic stage and M stage." (PMID 35141222, 2022). "Althought our research revealed that Mapk14 can be used as a colorectal cancer biomarker, there are still further experiments and analysis that need to be considered." (PMID 35141222, 2022). "Kaplan-Meier and timeROC GSE17537 datasets were obtained from the Gene Expression Omnibus (GEO) dataset to assess the prognostic impact of the Mapk14 gene on colorectal cancer." (PMID 35141222, 2022). "A previous study showed elevated expression of CORO2A in colorectal carcinoma tissues, and a link between its expression and oncogenic MAPK14 and PRMT5 signaling pathways." (PMID 34884487, 2021). "This is also in accord with previously reported data showing the detrimental effect of MAPK14/p38a inhibition on proliferation and survival of colorectal cancer cells, leading to cell cycle arrest and autophagy-mediated cell death." (PMID 25633290, 2015). "In addition, the Mapk14 protein expression levels were significantly higher in colorectal cancer tissues at the M0 and M1 stage than in normal tissues adjacent to cancer in the M stage." (PMID 35141222, 2022). "Importantly, the abnormal overexpression of Mapk14 in colorectal cancer is related to the level of immune infiltration of immune cells (including CD8+ T cells, neutrophils, dendritic cells, B cells, CD4+ T cells, and macrophages)." (PMID 35141222, 2022). "The studies have indicated that increased MAPK8 plays a critical role in the development of colorectal cancer, and MAPK14 downregulation could effectively impede the poor behaviors of the clear cell renal cell carcinoma." (PMID 36438897, 2022). "In addition, Mapk14 expression was significantly correlated with the immune score and immune checkpoint in colorectal cancer." (PMID 35141222, 2022). "A drug sensitivity analysis was performed, and it showed that the expression of Mapk14 was positively correlated with most drugs, which further confirmed that drugs targeting Mapk14 may play a therapeutic role in colorectal cancer." (PMID 35141222, 2022). "Function analyses indicated that MSARCD3 might promote CAFs activation and colorectal cancer metastasis through SMARCD3-WNT5A/TGF-β-MAPK14-SMARCD3 positive feedback loop." (PMID 33125346, 2020).
colorectal cancer (continued). "For the first time, we demonstrated that SMARCD3 was a novel prognostic marker that mainly expressed in CAFs and might promote CAFs activation and colorectal cancer metastasis through SMARCD3-WNT5A/TGF-β-MAPK14-SMARCD3 positive feedback loop." (PMID 33125346, 2020). "PPI network analysis demonstrated that SMARCD3 could physically interacted with MAPK14 (p38α), MYOD1 and SMAD4 etc., which indicated mechanistic insights underlying SMARCD3 related colorectal cancer metastasis." (PMID 33125346, 2020). "Further PPI analysis indicated that SMARCD3 might promote colorectal cancer metastasis through MAPK14, MYOD1 or SMAD4 related pathways." (PMID 33125346, 2020). "Furthermore, Rac1 and Mapk14 connected leukocyte transendothelial migration pathway with the pathways of colorectal cancer, renal cell carcinoma, osteoclast differentiation." (PMID 32632500, 2020). "To investigate whether Mapk14 expression can be used as a prognostic marker for colorectal cancer patients, we evaluated the distribution of Mapk14 expression levels and its relationship with patient Disease-free survival (DFS) and Disease Specific Survival (DSS) using the GSE17537 dataset." (PMID 35141222, 2022). "Furthermore, the relationship between SIGLEC15,TIGIT,LAG3,CTLA4, PDCD1LG2 immune checkpoints and Mapk14 was only verified by correlation analysis, and we need to further explore the mechanism of Mapk14 expression in colorectal cancer in vitro and vivo experiments, such as single cell RNA sequencing." (PMID 35141222, 2022). "In summary, Mapk14 may play a key regulatory role in the carcinogenesis of colorectal cancer." (PMID 35141222, 2022). "For RIG-I-like receptor signaling pathway in colorectal cancer, MAPK9, MAPK14, MAP3K7, and RELA were enriched in the pathway." (PMID 39211773, 2024). "Three significant subfamilies of MAPK are involved in the pathophysiology of colorectal cancer (CRC): ERK, c-Jun N-terminal kinase or stress-activated protein kinases (JNK or SAPK), and MAPK14." (PMID 38102686, 2023). "Using colorectal cancer data, we showed that SMARCD3 expression was positively correlated with WNT5A, TGF-β and p-MAPK14, which were consistent with previous reports." (PMID 33125346, 2020). "To investigate the interactions between the tumor immune microenvironment and single cells, we used the online scTIME tool for Mapk14 analysis of tumor immune microenvironment specificity and applied the GSE108989 dataset for single-cell transcriptome visualization in colorectal cancer." (PMID 35141222, 2022). "MAPK14, a core molecule of the MAPK pathway, plays vital roles in the colorectal cancer (CRC)." (PMID 34709743, 2021). "However, the biological function of Mapk14 gene in colorectal cancer has not been elucidated." (PMID 35141222, 2022).
glioblastoma (13 papers, 2015 to 2024). The most malignant astrocytic tumor (WHO grade IV). "Dual inhibition of MAPK11 and MAPK14 is currently being tested as a monotherapy or in combination with other agents, such as gemcitabine and carboplatin, for the treatment of glioblastoma, ovarian, and metastatic breast cancer." (PMID 39666682, 2024). "Its direct binding to MAPK14 was further validated in vitro, and inhibition of MAPK14 kinase activity was confirmed in live glioblastoma cells." (PMID 33021050, 2020). "By combining transcriptomic analysis, molecular docking, and functional assays (biophysical, biochemical, and cellular), we validated MAPK14 as a critical target of mebendazole and a key player in glioblastoma progression." (PMID 33021050, 2020). "MAPK14 expression was found to be elevated in glioma cells, which is in contrast to the findings of other studies, which indicated that the expression of this gene was decreased in glioblastoma samples." (PMID 36142793, 2022). "Finally, gene silencing demonstrated that MAPK14 is involved in glioblastoma tumor spheroid growth and response to mebendazole treatment." (PMID 33021050, 2020). "For example, miR-124 alleviates cell death in the process of AD by targeting BACE1, while increases cell death in glioblastoma by regulating TEAD1, MAPK14/p38α, and SERP1." (PMID 26041995, 2015). "Therefore, several novel specific inhibitors of MAPK14 are currently tested in phase I and II trials for diverse non-HCC cancer types like metastatic breast cancer and adult glioblastoma." (PMID 33803354, 2021).
glioma (13 papers, 2010 to 2025). A benign or malignant brain and spinal cord tumor that arises from glial cells (astrocytes, oligodendrocytes, ependymal cells). "Previous studies have identified MAPK14 (p38) and KDR as potential tumour suppressors in glioma development and potential antigens for vaccine advancement." (PMID 37865727, 2023). "Decreasing the level of miR-155 expression sensitizes glioma cells to the temozolomide (TMZ) by targeting the p38 isoforms MAPK13 and MAPK14." (PMID 30583549, 2018). "Furthermore, analysis of TCGA datasets revealed p38α (MAPK14) was upregulated in glioma samples compared to non-tumor samples." (PMID 38806469, 2024). "Tyrosine-specific phosphoproteomic analysis of IL-33+ tumors showed an increase in a number of phospho-peptides derived from STAT3, CDK1, CDK2, FYN, MAPK14, and MAPK3, some that based on amino acid sequence could be attributed to either human glioma or mouse host origin." (PMID 33020472, 2020).
Insulin resistance (13 papers, 2016 to 2025). Increased resistance towards insulin, that is, diminished effectiveness of insulin in reducing blood glucose levels. "Integration of compound, target, and pathway data positioned IL-6 as a central mediator, interacting with MAPK1, MAPK3, MAPK14, PTGS2, and BCL2, genes associated with inflammation-induced insulin resistance and adipocyte dysfunction." (PMID 41382285, 2025).
prostate carcinoma (12 papers, 2009 to 2025). A carcinoma that arises from epithelial cells of the prostate gland. "Through systematic analysis of nine high‐risk contaminants, we identified pan‐cancer targets and key pathway modules, with subsequent validation of hub genes (JUN, CDC42, MAPK14) in breast, colon, and prostate cancers using TCGA datasets." (PMID 41246859, 2025). "Second, we found a five-fold increase in MAPK14 expression in prostate cancer cells on exposure to −10°C freezing temperature (unpublished data)." (PMID 19513079, 2009). "A combination of chloroquine as an autophagy inhibitor and palladium (II) barbiturate complex results in inhibition of PI3K-AKT signaling, MTOR and MAPK14/p38 upregulation to inhibit protective autophagy and potentiate apoptosis induction in prostate cancer cells." (PMID 35317831, 2022). "Integration of these results with the machine learning approaches identified MAPK14 and CDC42 as potential key regulators in prostate cancer progression." (PMID 41246859, 2025).
rheumatoid arthritis (12 papers, 2006 to 2026). A chronic, systemic autoimmune disorder characterized by inflammation in the synovial membranes and articular surfaces. "An essential role of the p38α (MAPK14) pathway in inflammatory responses and inflammatory diseases including rheumatoid arthritis and chronic obstructive pulmonary disease is well-established." (PMID 39923112, 2025).
Alzheimer disease (10 papers, 2014 to 2025). A progressive, neurodegenerative disease characterized by loss of function and death of nerve cells in several areas of the brain leading to loss of cognitive function such as memory and language. "The mechanism of Alzheimer's disease is that MAPK14/P38A activates the targeting neurons to regulate autophagy." (PMID 35003290, 2021). "This provides the first in vivo demonstration of the effects of selective reduction of MAPK14 activity on autophagy and suggests that therapeutic inhibition of MAPK14 has the potential to address the autophagic defect in Alzheimer disease." (PMID 27715387, 2016). "As such, the results suggest that targeting MAPK14 activity may be a means to ameliorate the defect in autophagic-lysosomal protein degradation that has otherwise been demonstrated in Alzheimer disease." (PMID 27715387, 2016). "↓ of kinase expression (5 μM): GSK3β, CDK5, DYRK1A, CAMK2A, MAPK1, MAPK12, MAPK14.Modulation of the hGMSC transcriptome, ↓ expression of genes involved in Alzheimer's pathogenesis.↓ expression of GSK3b and p‐GSK303B2, which plays a key role in Alzheimer's disease." (PMID 39653426, 2025).
ovarian carcinoma (10 papers, 2014 to 2023). A malignant neoplasm originating from the surface ovarian epithelium. "Next, we determined the phosphorylation of EphB4 and its downstream adaptor protein Crk1 (MAPK14) in lysates from human A2780cp20 ovarian cancer cells by immunoprecipitation with anti-EphB4 and anti-Crk1 antibodies followed by immunoblotting with phospho-specific antibodies." (PMID 31949258, 2020). "Because ErbB2 was reported to be expressed in chondrocytes and GDF15 was observed to interact with this receptor in ovarian cancer, we demonstrated that this interaction was conserved in chondrocytes and may have partially explained the mechanism of the GDF15/MAPK14 signaling pathway." (PMID 35806043, 2022).